INS (insulin)
Diseases named in the same sentence as INS in open-access papers (continued):
Sharing a sentence is not in itself a finding about the gene and the disease.
Hyperinsulinemia (continued). "As mentioned in the section above, a normal pregnancy generally follows a pattern of hyperinsulinemia and a progressive decrease in insulin sensitivity, which means that at early gestation, pregnant women are more insulin sensitive than at late pregnancy." (PMID 39083072, 2024). "Recent data suggest that a threshold of 0.1 g of NSC/kg BW/meal is prudent to avoid hyperinsulinemia in insulin-dysregulated (ID) horses." (PMID 39682351, 2024). "The mechanism of IR is currently studied as a biological response to impaired insulin stimulation in the liver, muscle, and adipose tissue, resulting in hyperinsulinemia." (PMID 37937558, 2024). "Research by Cristina Bosetti and colleagues suggests that AS such as saccharin can induce pancreatic cells to release insulin, resulting in short-term hyperinsulinemia." (PMID 38324548, 2024). "Findings suggest that compensatory hyperinsulinemia surpasses IR’s binding capability, allowing insulin to become attached to IGF receptors." (PMID 38255795, 2024). "Due to the distinct mechanisms of action exhibited by myo-inositol and metformin in enhancing insulin sensitivity and regulating hyperinsulinemia, the combined use results in an additive effect for improving clinical outcomes." (PMID 39803009, 2024). "For instance, DEHP activates PPARs, diminishing insulin sensitivity while stimulating insulin secretion, consequently inducing hyperinsulinemia." (PMID 38903577, 2024). "Biochemical analysis revealed markedly elevated insulin and C-peptide levels, indicative of endogenous hyperinsulinemia." (PMID 39677258, 2024). "IDE can degrade insulin in multiple intracellular compartments and genetic ablation of Ide results in hyperinsulinemia which suggests IDE plays a central role in insulin homeostasis." (PMID 38767782, 2024). "For insulin, the average value calculated for the whole study population was equal to 29.0 μIU/mL, indicating hyperinsulinemia (cut-off equal to 24.9 μIU/mL was adopted from the laboratory standards)." (PMID 39407760, 2024). "Due to the insulin resistance of the peripheral tissues, the pancreas compensates by producing more and more insulin, which results in beta-cell hypertrophy and hyperinsulinemia." (PMID 39452932, 2024). "Overall, these results suggest that chronic hypercaloric intake (overnutrition) increases pancreatic insulin secretion, leads to chronic hyperinsulinemia and increases subcutaneous fat." (PMID 38791525, 2024). "It amplifies the demand for insulin secretion, leading to hyperinsulinemia and subsequent metabolic disturbances." (PMID 39408856, 2024). "This diminished efficacy of insulin prompts the pancreas to produce more insulin, leading to hyperinsulinemia." (PMID 39198298, 2024). "It seems that insulin secretion drives the postprandial decline of homocysteine since physiological hyperinsulinemia can stimulate homocysteine metabolic clearance." (PMID 38255980, 2024). "Firstly, it should be noted that leucine and isoleucine have been reported to be insulin secretagogues, contributing to chronic hyperinsulinemia and β-cell failure." (PMID 39261864, 2024). "The term “ID” is an all-encompassing term to describe any abnormality in insulin metabolism manifesting in hyperinsulinemia." (PMID 39687851, 2024). "For instance, heterozygosity of the Insulin Pathway effector chico in insulin-producing cells (IPCs) results in hyperinsulinemia by upregulating Drosophila insulin Dilp2." (PMID 38172609, 2024). "High levels of eGDR indicate better insulin sensitivity, and in this study, eGDR showed a negative correlation with female infertility, suggesting that IR, which leads to hyperinsulinemia, negatively impacts reproductive health." (PMID 39600947, 2024). "Hyperinsulinemia and increased levels of insulin growth factors have been shown to promote cell proliferation in chronic inflammatory conditions, such as MASH and chronic HCV infection." (PMID 39585028, 2024).
Hyperinsulinemia (continued). "A similar strategy, using a combination of diazoxide (to reduce hyperinsulinemia) and metformin (to increase insulin sensitivity) also achieved relatively minimal results, but with the side effects of oedema and liver dysfunction." (PMID 38019584, 2024). "Although the adverse effects of hyperinsulinemia have already been reported in the medical literature, insulin secretagogues and insulin continue to be actively administered as drug therapy for type 2 DM in clinical practice." (PMID 38304078, 2024). "The visceral adiposity that is common in obese and non-obese women with PCOS worsens all metabolic and reproductive outcomes, increasing insulin resistance, compensatory hyperinsulinemia, as well as adipogenesis and decreased lipolysis." (PMID 38673649, 2024). "Those with lower educational and income levels were also more likely to have higher insulin levels and a greater prevalence of hyperinsulinemia and IR." (PMID 39606490, 2024). "In these conditions, the pancreas produces more insulin to overcome the resistance, resulting in hyperinsulinemia, which can be the primary mediator of metabolic syndrome, leading to type 2 diabetes and cardiovascular diseases." (PMID 39618714, 2024). "Elevated serum insulin concentrations in both T1DM groups compared to control animals suggest a state of hyperinsulinemia in these animals likely as a result of exogenous insulin treatment." (PMID 38435452, 2024). "The study results show that adding Cur to the diet can positively reduce insulin levels, improve IR, and lead to faster recovery of hyperinsulinemia." (PMID 39618714, 2024). "In response, hepatocytes turn down the glucose discharge channel favoring blood glucose control, and β cells secret less insulin to attenuate hyperinsulinemia." (PMID 39873003, 2024). "IR is characterized by reduced sensitivity of the body’s cells to insulin, which diminishes the efficacy of the hormone and thereby leads to an overproduction of insulin (i.e., hyperinsulinemia)." (PMID 39261457, 2024). "Hyperinsulinemia promotes tumor growth and progression through its mitogenic effects by activating insulin and insulin-like growth factor (IGF) signaling pathways." (PMID 39290325, 2024). "Oral insulin mimics the normal insulin absorption pathway to establish a portal-peripheral insulin gradient, which avoids peripheral hyperinsulinemia raised by frequent subcutaneous injections." (PMID 38214820, 2024). "During weight gain, decreased glucose uptake by insulin-resistant skeletal muscle leads to compensatory hyperinsulinemia." (PMID 39585028, 2024). "With time, blood glucose levels rise in tandem with reductions in insulin secretion as this compensatory hyperinsulinemia starts to falter." (PMID 38398039, 2024). "Due to a lack of diminished central feedback on the beta cells/liver’s insulin production via the vagus nerve, we observed hyperinsulinemia." (PMID 38248469, 2024). "Clinicians should develop strategies aimed at maintaining insulin sensitivity and managing hyperinsulinemia throughout a woman’s reproductive years to support overall fertility health." (PMID 38310251, 2024). "Persistent hyperinsulinemia potentially results in decreased insulin sensitivity, but it is also possible that the hyperinsulinemic response to milk has a positive or even protective impact on blood glucose regulation, especially in those with T2D." (PMID 39272602, 2024). "Laboratory findings revealed elevated endogenous insulin and C-peptide levels, indicating hyperinsulinemia." (PMID 39677258, 2024). "Our analysis of CD4+ T cells from RA patients with hyperinsulinemia revealed that insulin exerts a strong immunosuppressive effect on Th1 cells and regulates cell cycle progression, consistent with findings from in vitro experiments." (PMID 39768214, 2024).
Hyperinsulinemia (continued). "An important characteristic of the metabolic syndrome is hyperinsulinemia, which is brought on by excessive β-cell insulin production and has been connected to the development of T2DM and cardiovascular disease." (PMID 39768947, 2024). "The human body, to manage the impaired insulin action, further enhances a compensatory insulin secretion, resulting in hyperinsulinemia." (PMID 39201799, 2024). "Both A. muciniphila treatment and dietary intervention increased first-phase insulin secretion, and alleviated hyperinsulinemia and IR in the rats with pre-DM." (PMID 38763955, 2024). "Horses with elevated baseline insulin values (>20 μU/mL) from both groups experienced a more marked hyperinsulinemia, reaching a mean peak insulin of 197.5 μU/mL as compared to 90.06 μU/mL in those with normal baseline insulin." (PMID 38828366, 2024). "BMS is superior to drug therapy for reducing hyperinsulinemia, and improving insulin sensitivity, both of which are optimal for treating PCOS." (PMID 38529391, 2024). "She developed severe hyperinsulinemia, low C-peptide levels, positive insulin antibodies, poor postprandial glycemic control, and occasional autonomic nervous system symptoms such as hunger, palpitations, fatigue, and excessive sweating." (PMID 39575003, 2024). "In conclusion, cancer can develop in both individuals with normal insulin levels and those with hyperinsulinemia." (PMID 39290325, 2024). "As an outcome, the pancreas produces more insulin is being produced to recompense for the diminished sensitivity which leads to advanced insulin levels in the bloodstream called hyperinsulinemia." (PMID 38371502, 2024). "The influence of insulin on breast cancer is mainly based on the effect of IR or hyperinsulinemia, which activates the extracellular-related-kinase cascade and the AKT pathway through activation of the insulin receptor or the IGF receptor in breast cancer." (PMID 38904041, 2024). "Recently, IR can be defined as an impaired response to insulin stimulation of tissue cells so that hyperinsulinemia takes place consequently." (PMID 39309107, 2024). "Taking the risks of hyperinsulinemia into consideration, we are just aware of the need for insulin-independent therapies." (PMID 38304078, 2024). "This condition, called hyperinsulinemia, begins with the development of IR and can be identified in cancer patients because insulin plays the role of an oncogenic factor." (PMID 38392069, 2024). "Endogenous hyperinsulinemia or hyperinsulinemic hypoglycemia is defined by low blood sugar levels with concurrently high insulin and C-peptide levels." (PMID 39188435, 2024). "The results suggest that in our sample increased insulin production (i.e. hyperinsulinemia) was sufficient to prevent large glucose variability." (PMID 39261457, 2024). "A comprehensive glucose tolerance test conducted upon admission indicated a significant increase in insulin levels following glucose intake, suggestive of hyperinsulinemia." (PMID 39605025, 2024). "Most women diagnosed with PCOS prior to pregnancy present with reduced insulin sensitivity, hyperinsulinemia, and normoglycemia." (PMID 38541997, 2024). "In the obese state, hyperinsulinemia results from increased insulin secretion, but also from impaired clearance." (PMID 38767782, 2024). "B. uniformis-treated HFHSD-fed mice showed improved oral glucose tolerance along with reduction of the HFHSD-induced hyperinsulinemia and restoration of insulin secretion after an oral glucose challenge." (PMID 38845049, 2024). "Hyperinsulinemia (insulin is a hormone that reduces blood glucose levels), is common during P. falciparum malaria." (PMID 39492784, 2024). "Type 2 diabetes (T2DM) occurs due to insulin resistance, a pathological condition characterized by the inability of the cells to respond to insulin or the downregulation of insulin receptors in response to hyperinsulinemia." (PMID 39000136, 2024).
Hyperinsulinemia (continued). "The main abnormality among Africans from sub-Saharan Africa is hyperinsulinemia, which is brought on by a combination of decreased hepatic insulin clearance and increased insulin secretion." (PMID 39712180, 2024). "With regard to the effects of hyperinsulinemia on BC pathogenesis, these are mediated by the powerful mitogen potential of insulin." (PMID 39408212, 2024). "Due to leptin resistance in obese patients, the inhibitory effect of leptin on insulin secretion is weakened, which interferes with the “adipose-insulin axis”, and thus also aggravates hyperinsulinemia." (PMID 38348417, 2024). "The same authors highlighted a significant statistical relationship between AIP and basal insulin, identifying this index as a potential marker for hyperinsulinemia." (PMID 38920551, 2024). "This can identify post-load hyperinsulinemia, late insulin peak, and prolonged insulin response correctly in normal weight/lean PCO syndrome patients, such as high basal insulin, and high HOMA index in overweight/obese patients." (PMID 38337532, 2024). "Previously, we have shown that this animal model develops both reproductive and metabolic features of the syndrome, including decreased systemic insulin sensitivity and hyperinsulinemia." (PMID 39268230, 2024). "Our study showed that males consistently had higher insulin levels and a greater prevalence of hyperinsulinemia and IR compared to females, although females exhibited a more rapid increase in these conditions over the last four cycles." (PMID 39606490, 2024). "Additional studies are needed to further define the clinical impact of hyperinsulinemia and impaired insulin sensitivity in dogs." (PMID 38825593, 2024). "In both cultured CD4+ cells and those isolated from patients with hyperinsulinemia, insulin inhibited IFNγ production by repressing key Th1 transcription factors and cell surface receptors essential for IFNγ signaling." (PMID 39768214, 2024). "This correlation provides an opportunity to use serum SHBG values to characterize insulin sensitivity/hyperinsulinemia." (PMID 38337532, 2024). "The patient should be effectively managed with a continuous insulin delivery system, which reduces the variation of blood insulin levels, preventing diabetic ketoacidosis episodes as well as hyperinsulinemia." (PMID 39170998, 2024). "IR refers to a diminished sensitivity to insulin in the body, characterized by hyperinsulinemia resulting from abnormal serum insulin levels." (PMID 39765819, 2024). "Even a low increase in peripheral blood ketosis, induced with the KD, can reduce stress connected with hyperinsulinemia, improve sensitivity to peripheral insulin, lower external demand for insulin and slow down insulin secretion." (PMID 39463845, 2024). "Studies in human models have identified inhibited insulin-associated PI3K/Akt/mTOR pathways and an association between hyperinsulinemia, lower insulin sensitivity, and MASLD." (PMID 39512967, 2024). "If this state persists, it can result in hyperinsulinemia, characterized by abnormally high insulin levels." (PMID 39734671, 2024). "It has been generally accepted that an elevated insulin level (hyperinsulinemia) indicates a common phenomenon in PDAC patients and a signal for poor clinical outcomes." (PMID 38827297, 2024). "For example, hyperinsulinemia can transform scrib−/− cells from ‘losers’ into ‘winners’ by upregulating insulin-mTOR signalling, a pathway regulating protein synthesis." (PMID 38172609, 2024). "By integrating continuous glucose monitoring (CGM), dietary data, and other physiological inputs, the DT provides individualized dietary recommendations to improve insulin sensitivity, reduce hyperinsulinemia, and support the remission of T2D." (PMID 39634180, 2024). "Chronic consumption of high-fat food, possibly by inducing hepatic oxidative and ER stress, can reduce the amount of IDE enzyme protein and hepatic clearance of insulin and eventually result in hyperinsulinemia." (PMID 38975085, 2024).
Hyperinsulinemia (continued). "HFPG induces compensatory hyperinsulinemia, which, over the long term, can result in insulin signaling defects in tissues normally responsive to insulin." (PMID 38667768, 2024). "After 150 days, there was significant fasting hyperinsulinemia as well as higher insulin concentrations following the OGT." (PMID 38473112, 2024). "Hypertension in the insulin-resistant state and in hyperinsulinemia is primarily mediated by the insulin-induced stimulation of renal reabsorption of Na+." (PMID 39120943, 2024). "Simulating hyperinsulinemia to study insulin signaling defects.Commonly used at 100-1000 nM insulin for 24-48h." (PMID 39749015, 2024). "In ovaries, insulin binds to IGF receptors due to compensatory hyperinsulinemia or elevated insulin levels." (PMID 38468402, 2024). "Weight loss can reduce adipose tissue, particularly visceral fat, improving insulin sensitivity in the liver and muscles, thereby lowering hyperinsulinemia." (PMID 39469573, 2024). "At 120 min of euglycemic-hyperinsulinemia, the steady-state glucose infusion rate averaged 2.5 ± 0.5 mg/kg/min and the steady-state plasma insulin concentration 126 ± 16 mIU/L." (PMID 38170166, 2024). "Hyperinsulinemia is a compensatory response characterized by elevated circulating insulin levels due to pancreatic β-cell hypersecretion." (PMID 39741509, 2024). "Insulin suppressed IFNγ production and induced the senescence-associated secretome in CD4+ cell cultures and in patients with hyperinsulinemia." (PMID 39768214, 2024). "Physiological euglycemic hyperinsulinemia induced by insulin infusion in healthy volunteers acutely reduced urinary UA, suggesting a significant contribution of insulin to the pathogenesis of hyperuricemia." (PMID 38474414, 2024). "These alterations lead to reduced insulin secretion, prompting compensatory elevation in insulin production and subsequent hyperinsulinemia." (PMID 38732634, 2024). "When the effector organs of insulin action (e.g., liver, skeletal muscle, adipose tissue) become less sensitive to insulin, there is a compensatory increase in insulin, eventually leading to hyperinsulinemia." (PMID 39081791, 2024). "TRF improved insulin sensitivity and reduced hyperinsulinemia, liver steatosis, inflammation, and fibrosis." (PMID 38672595, 2024). "All of them had normal fasting glycemia and lipid profiles; in 2 out of 10 cases, a condition of hyperinsulinemia (fasting insulin > 15 mUI/mL) was diagnosed." (PMID 38540345, 2024). "Our patient had a very high titre of fasting insulin >1000, which is very rare in other conditions of endogenous hyperinsulinemia." (PMID 38428138, 2024). "Due to the anabolic impact of insulin on bone metabolism, people with hyperinsulinemia demonstrate an increased BMD." (PMID 39741509, 2024). "In a hyperinsulinemia state, elevated insulin levels lead to increased production of IGF-1 due to upregulated growth hormone receptor (GHR) signaling." (PMID 39410536, 2024). "This leads to compensatory hyperinsulinemia, which is an increased production of insulin by the pancreas." (PMID 38666802, 2024). "The insulin-sparing effect across these populations is supportive of this being a SDC that can represent a healthier carbohydrate, given that induced hyperinsulinemia has been associated with long-term deleterious effects." (PMID 39195506, 2024). "Fetal hyperinsulinemia can alter placental mRNA expression, leading to the dysregulation of insulin/insulin-like growth factor (IGF) systems." (PMID 38605306, 2024). "Disturbances in insulin secretion due to insulin resistance results in compensatory insulin hypersecretion, usually at levels at which normoglycemia cannot be maintained, leading to hyperinsulinemia." (PMID 38397072, 2024). "Two studies analyzing the chronic effects of insulin on muscle adaptation in response to exercise stimuli have shown that hyperinsulinemia potentiates muscle hypertrophy, amino acid uptake in myocytes, and protein synthesis." (PMID 39420894, 2024).